FURIN (furin, paired basic amino acid cleaving enzyme)
Diseases named in the same sentence as FURIN in open-access papers (continued):
Sharing a sentence is not in itself a finding about the gene and the disease.
Hypertension (continued). "Multivariate logistic regression analysis revealed that age, history of DM or hypertension, blood urea, serum creatinine, FURIN (G/C + C/C) genotypes, and IFNL4 T/T homozygous were independent risk factors associated with increased mortality." (PMID 38703289, 2024). "In our study, genetic variants in FURIN associated with CVD and hypertension confirming previous reports." (PMID 36188622, 2022). "Recently, FURIN was suggested to be a potential biomarker of hypertension and cancer, reflecting the involvement of this broadly expressed proprotein convertase in many critical biological processes." (PMID 36188622, 2022). "So far, there are no reports about the relationship between genetic variations in the human FURIN gene and hypertension, or the genotyping of their representative variations in the general population." (PMID 20707915, 2010). "The present study is the first to examine the relationships between genetic variations in the FURIN gene and hypertension in humans." (PMID 20707915, 2010). "We propose that genetic variations of the FURIN gene collectively contribute to the pathogenesis of hypertension in the Xinjiang Kazakh and Uygur populations." (PMID 20707915, 2010). "Because these systems influence blood pressure regulation, we considered FURIN as a candidate gene for hypertension." (PMID 20707915, 2010). "In this study, we investigated whether FURIN variants exhibited significant associations with PEH among Black and White adults with elevated BP to Stage 1 hypertension." (PMID 30706700, 2019). "As such, we hypothesize that both common rare genetic variations in the FURIN gene may contribute to hypertension." (PMID 20707915, 2010). "Regarding the four prioritized proteins, individuals on BP medications had significantly lower circulating levels of FURIN and MST1, compared to individuals with hypertension but not on BP medication, even after excluding individuals with diabetes or lipid-lowering medications." (PMID 41065563, 2026).
schizophrenia (15 papers, 2018 to 2026). A major psychotic disorder characterized by abnormalities in the perception or expression of reality. "In a study examining RNA-seq from over 500 dorsolateral prefrontal cortices, FURIN emerged as one of five single-gene loci implicated in schizophrenia." (PMID 36386965, 2022). "We further detected ∆9-tetrahydrocannabinol-induced upregulation of FURIN in patient-derived cerebral organoids, an effect observed in both control and schizophrenia cell lines." (PMID 40827685, 2026). "Variants in FURIN have been associated with other brain- and SUD-related phenotypes, most predominantly schizophrenia, but also risk taking, number of sexual partners, and insomnia." (PMID 36207451, 2022). "Dysregulation of the genes FURIN, TSNARE1, CNTN4, CLCN3 and SNAP91 have been implicated by eQTL analysis of schizophrenia GWAS hits, which were later separately prioritized by chromatin interaction analysis of schizophrenia risk variants." (PMID 35972862, 2022). "The FURIN mRNA expression is decreased in the prefrontal cortex of schizophrenia (SCZ) patients, whereas increased protein levels of furin are found in the temporal cortex of epilepsy patients." (PMID 35996194, 2022).
viral infection (11 papers, 2020 to 2025). "Genomic studies have identified numerous variants in the FURIN gene that significantly influence viral infection processes, either through direct effects on viral protein processing or by altering key physiological pathways, including cardiovascular, metabolic, and immunological homeostasis." (PMID 41301448, 2025). "Conversely, FURIN activity can also aid in viral infection, the most notable recent example being that of coronavirus SARS-CoV-2." (PMID 38607027, 2024). "To confirm that the expression of ACE2, TMPRSS2, and FURIN in adult human inner ear tissue facilitates viral infection, we exposed explanted human vestibular tissue to conditioned media (“mock”) or SARS-CoV-2." (PMID 34870285, 2021). "FURIN: FURIN is an essential cleavage enzyme for the spike protein of SARS-CoV-2 in the virus infection process." (PMID 34109284, 2021). "However, the involvement of FURIN in the virus infection pathway remains to be confirmed by future experimental approaches." (PMID 32246845, 2020). "In particular, FURIN regulates angiotensin-converting enzyme 2 (ACE2), which is implicated in the viral infection, and irisin treatment decreases FURIN expression, establishing a link between ECM organization, irisin, and the putative response to viral infection in obesity conditions." (PMID 33803198, 2021). "Indeed, many CF patients are treated with low-dose long-term azithromycin, which is known to suppress viral infection and lung inflammation and which inhibits the activity of FURIN, one of the serine proteases involved in the facilitation of SARS-CoV-2 cellular entry, via the ACE2 receptor." (PMID 33182847, 2020). "In addition, we also profiled the expressions of the known cofactors of ACE2, i.e., TMPRSS2, FURIN, and NRP1, which also play roles during the viral infection and are also conserved between human and the mammalian species investigated above." (PMID 33392409, 2021). "We have not found any particular relation between them; however, some of them might play a role in processes such as protein synthesis regulation in cardiomyocytes (PABPC1), cardiac differentiation and development (FURIN; ADAR), or cellular response to viral infection (TMED2)." (PMID 33917391, 2021).
atherosclerosis (10 papers, 2020 to 2024). A disease characterized by the build-up of fatty material and calcium deposition in the arterial wall resulting in partial or complete occlusion of the arterial lumen. "FURIN is a potential therapeutic target associated with many diseases, including atherosclerosis and cancer, and therefore there has been considerable research into the development of FURIN inhibitors." (PMID 37443715, 2023). "There is accumulating evidence indicating that FURIN plays an important role in atherosclerosis, the pathological condition underlying CAD." (PMID 37443715, 2023). "Previously, we performed a systemic inhibition of FURIN in a mouse model of atherosclerosis and demonstrated significant plaque reduction and alterations in macrophage function." (PMID 38607027, 2024). "This genetic finding was subsequently validated in two independent mouse models of atherosclerosis, where the systemic inhibition of FURIN was found to provide atheroprotection as well as reduce restenosis." (PMID 38607027, 2024). "In experimental KO models, irreversible inhibition of FURIN (via α1-antitrypsin) attenuates the progression of atherosclerosis." (PMID 37940228, 2023). "We used the endothelial marker gene CDH5 to identify a cluster of endothelial cells and confirmed that these cells express DHX38, MAT2A, CCDC92, FES and FURIN, prompting future efforts to dissect the role of these genes in this cell type in atherosclerosis." (PMID 36928188, 2023). "In atherosclerosis, we found that the expression of FURIN, PCSK5 and MBTPS1 was significantly lower in carotid plaques vs. normal artery controls, while PCSK6 and PCSK7 were increased." (PMID 36188622, 2022). "Accumulating evidence suggests that FURIN plays a critical role in atherosclerosis through regulation of lipid metabolism and vascular inflammation." (PMID 32425817, 2020). "Furthermore, pathway and gene-set enrichment analysis of 9889 cases and 11,089 controls in seven CAD GWAS datasets identified FURIN as likely to be a critical component in several pathways in atherosclerosis and CAD development." (PMID 39273186, 2024). "In atherosclerotic plaques, FURIN has been detected in macrophages, smooth muscle cells, and endothelial cells.A key process in the development and progression of atherosclerosis is the recruitment of monocytes into the arterial wall and atherosclerotic lesions." (PMID 37443715, 2023). "FURIN plays a regulatory role in inflammation and atherosclerosis." (PMID 37940228, 2023). "FURIN is also involved in activation of proBNP, PCSK9, and ANGPTL, which each contribute to the development of atherosclerosis." (PMID 37940228, 2023). "While we cannot exclude FURIN as an excellent candidate causal CAD gene, our base editing experiment suggests that there might be >1 causal genes at this locus and that FES should be tested in future experiments aimed at determining its precise biological function(s) in atherosclerosis." (PMID 36928188, 2023). "Our study also identified specific atherosclerosis-related transcription factors KLF4, KLF11 and BCLAF1 upstream from FURIN, PCSK6 or PCSK7." (PMID 36188622, 2022).
diabetes (8 papers, 2020 to 2026). "In a different study using the same population, He and colleagues suggested an association between the hypermethylation of the FURIN promoter, which mostly predicts lower furin protein levels and an increased risk of diabetes incidence." (PMID 37830621, 2023). "Although no direct evidence, previous findings from other dimensions supported the association between FURIN promoter hypermethylation and diabetes identified by our study." (PMID 35399937, 2022). "Because the temporal sequence is of considerable importance for causal inferences, we aimed to examine the prospective association between DNA methylation of FURIN promoter and incident diabetes during an average of 4 years of follow-up in the Gusu cohort." (PMID 35399937, 2022). "We tested and found a significant joint association of multiple CpG methylation sites in FURIN promoter with incident diabetes (P<0.001), using a gene-bases association analysis approach." (PMID 35399937, 2022). "Epigenetic studies in a candidate gene would help examination of the association between FURIN gene methylation and diabetes." (PMID 35399937, 2022). "Here, we aimed to examine the prospective association between DNA methylation in FURIN promoter and incident diabetes during 4 years of follow-up in Chinese adults." (PMID 35399937, 2022). "Our study is the first epidemiological study on FURIN promoter methylation concerning the risk of future diabetes and provides initial evidence for the potential role of FURIN promoter methylation in the pathogenesis of diabetes." (PMID 35399937, 2022). "Our results showed that hypermethylation of the CpG sites at the FURIN promoter could predict a higher risk of diabetes during an average 4-year follow-up in Chinese adults (OR=1.22, 95%CI: 1.05-1.43, for CpG1 and OR=1.39, 95%CI: 1.08-1.77, for CpG2)." (PMID 35399937, 2022). "Based on the studies above, we hypothesized that hypermethylation in FURIN promoter may suppress FURIN gene expression, thereby was associated with the development of diabetes." (PMID 35399937, 2022). "Therefore, the association between DNA methylation levels in FURIN promoter and diabetes needs to be further investigated and explored in multi-ethnic studies and large sample populations." (PMID 35399937, 2022). "We further examined whether DNA methylation levels at CpG1, CpG2, CpG7, and the average methylation level in the targeted region of the FURIN gene could improve the prediction performance for the risk of diabetes." (PMID 35399937, 2022). "In conclusion, our study demonstrated that hypermethylation in FURIN promoter at baseline could predict an increased risk of future diabetes in Chinese adults." (PMID 35399937, 2022). "Therefore, we examined the association between FURIN promoter methylation and incident diabetes." (PMID 35399937, 2022). "DNA methylation levels in FURIN promoter were quantified by target bisulfite sequencing using peripheral blood from 1836 participants in the Gusu cohort who were free of diabetes at baseline." (PMID 35399937, 2022). "It indicated that FURIN promoter methylation could serve as a predictor for the identification of individuals at high risk for diabetes during primary prevention, but more evidence is needed to establish the causality between FURIN promoter methylation and diabetes." (PMID 35399937, 2022). "FURIN promoter methylation may be a potential molecular modification that regulates furin expression underneath the relationship between furin and diabetes." (PMID 35399937, 2022). "FURIN promoter methylation may participate in the development of diabetes beyond lifestyles and metabolic factors." (PMID 35399937, 2022). "In the prospective cohort study of Chinese adults in the Gusu cohort, we demonstrated for the first time that FURIN promoter hypermethylation at baseline was significantly associated with an increased risk of future diabetes, independent of conventional risk factors." (PMID 35399937, 2022).
diabetes (continued). "This revealed high IP activity in the field of PCSKs, with patents ranging from biomarkers of diabetes (PCSK1 and PCSK2), to biomarkers and drug targets in cancer (FURIN and PCSK6), with the highest number of patents expectedly related to PCSK9." (PMID 36188622, 2022).
lung carcinoma (8 papers, 2013 to 2023). "FURIN has been shown to be high-expressed in various cancer types, including in lung cancer; moreover, the mRNA and protein levels of FURIN are associated with the invasiveness of lung cancer cell lines." (PMID 35668494, 2022). "We further compared the expression levels of CTSL, TMPRSS2, and FURIN in normal lungs and lung cancers." (PMID 35414771, 2022). "We show that ACE2 is co-expressed with membranous FURIN and/or TMPRSS2 in 16% of our NSCLC patient cohort, making these lung cancer cells susceptible to SARS-CoV-2 infection." (PMID 36077610, 2022). "Supporting a requirement for RIT1, AURKA, IGF1R, and FURIN in the proliferation of RIT1-mutant lung cancer, knockout of each gene significantly reduced cell proliferation of H2110iCas9 compared to cells expressing a non-targeting control guide (sgNTC)." (PMID 34373451, 2021). "High FURIN expression was found in non-small cell lung carcinomas (NSCLCs) vs. small cell lung carcinomas (SCLCs) and correlated with the aggressiveness of lung cancer cell lines." (PMID 23409034, 2013). "Furthermore, FURIN expression is a potential marker of lung cancer and therapeutic target." (PMID 35668494, 2022). "The results showed PLK1, LDHA, FURIN, FSCN1, and RAB27B were up-regulated in lung cancer tissues, and MS4A1 was down-regulated in lung cancer tissues." (PMID 37604869, 2023). "Compared to other proteases/proteinases/convertases such as TMPRSS2 and FURIN, the expression of CTSL was higher in both normal lungs and lung cancer samples." (PMID 35414771, 2022). "By further comparison of CTSL, TMPRSS2, and FURIN, all of which are proteinase/protease/convertases 43, 44, we found the expression of CTSL to be the highest in both in normal lungs and lung cancers." (PMID 35414771, 2022). "For instance, genetic silencing of FURIN inhibits processing of the insulin-like growth factor 1 receptor (IGF1R), migration, and invasion in lung cancers, which indicates that furin is a potential therapeutic target in lung cancers." (PMID 33968987, 2021). "These as well as more recent publications demonstrated altered expression of FURIN, PCSK1, PCSK2, and PCSK6 genes in lung cancer." (PMID 23409034, 2013). "Furthermore, we also found that PLK1, LDHA, FURIN, FSCN1, and RAB27B were increased in NSCLC cancerous cell lines compared with that in normal human bronchial epithelium cell line BEAS-2B, MS4A1 was down-regulated in lung cancer cells lines." (PMID 37604869, 2023).
asthma (5 papers, 2021 to 2023). "Multivariate linear regression analysis also showed that the transcript levels of FURIN in sputum was significantly associated with severe asthma and sputum neutrophilia." (PMID 33413387, 2021). "Sputum FURIN levels highly correlated with sputum neutrophils and were higher in an asthma endotype characterized by sputum neutrophilia and inflammasome activation signature." (PMID 33413387, 2021). "Levels of ACE2 and FURIN may differ by clinical or molecular phenotypes of asthma." (PMID 33413387, 2021). "Sputum ACE2 and FURIN transcripts were elevated in TAC2, an asthma endotype characterized by sputum neutrophilic inflammation and inflammasome activation signature." (PMID 33413387, 2021). "There are significant differences between the asthma cohorts that have been published so far that have looked at the expression of ACE2, TMPRSS2 and FURIN as compared to healthy controls." (PMID 33413387, 2021). "In conclusion, we found higher gene expression levels of ACE2 and FURIN in sputum of severe asthma compared to those of non-severe asthma." (PMID 33413387, 2021). "For example, studies in asthma patients showed elevated expression of ACE2, TMPRSS2, and FURIN in patients with severe but not mild-moderate asthma." (PMID 34262047, 2021).
Stroke (5 papers, 2022 to 2026). Sudden impairment of blood flow to a part of the brain due to occlusion or rupture of an artery to the brain. "Evidence of an association between the FURIN gene and stroke has also been demonstrated in population-based studies, with a recent multi-ancestry GWAS meta-analysis identifying FURIN as a putative causal gene." (PMID 39273186, 2024). "FURIN expression levels across tissues were associated with an increased stroke risk." (PMID 36180795, 2022). "Among these, genetically predicted levels of four proteins—ACOX1, FGF5, FURIN, and MST1—also demonstrated evidence of potential causal associations with CAD and/or stroke, supported by observational analysis." (PMID 41065563, 2026). "Proteome-wide MR identified 242 proteins associated with BP, of which 48 were also linked to CAD or stroke, with four (ACOX1, FGF5, FURIN, MST1) also supported by genetic colocalization analyses (FDR 5% and PP ≥70%)." (PMID 41065563, 2026). "Genetically predicted FURIN and FGF5 were strongly associated with BP and stroke risk, while ACOX1, FGF5, and MST1 exhibited potential causal effects on CAD." (PMID 41065563, 2026). "Of these, 5 proteins (ACOX1, BRAP, ERP29, FGF5, and FURIN) also showed strong colocalization with CAD and/or stroke and all had concordant direction of effects for BP and CAD and/or stroke." (PMID 41065563, 2026). "CELSR2, ABO, LPA, APOE, FGF5 and ZPR1 were related to both CHD and HF, while SH2B3 and FURIN were shared between CHD and stroke on MR analysis." (PMID 39322770, 2024).
glioma (4 papers, 2022 to 2025). A benign or malignant brain and spinal cord tumor that arises from glial cells (astrocytes, oligodendrocytes, ependymal cells). "Rs4702‐A was significantly associated with increased expression of FURIN and BDNF in the serum and PBMC of glioma patients after radiotherapy." (PMID 34953024, 2022). "In this study, by investigating the key indicators of radiotherapy‐induced cognitive impairment in glioma patients, we tried to unveil the role of G>A transformation of rs4702 polymorphism in 3’UTR of FURIN and the according signalling pathways." (PMID 34953024, 2022). "However, rs4702‐A was associated with increased expression of FURIN and BDNF in the serum and PBMC of glioma patients after radiotherapy." (PMID 34953024, 2022).